YBX1 (Y-box binding protein 1)
Diseases named in the same sentence as YBX1 in open-access papers (continued):
Sharing a sentence is not in itself a finding about the gene and the disease.
breast carcinoma (continued). "The expression levels of KMT2D and YBX1 were both upregulated in tumour tissues and correlated with poor prognosis for breast cancer patients." (PMID 38967349, 2024). "Elevated levels of the stem cell signature CD44, coupled with the ability to form mammospheres in trastuzumab-resistant breast cancer cells, are regulated by YBX1 phosphorylated at S102." (PMID 38255791, 2024). "YBX1 is consistently expressed in various human cancers, including pancreatic cancer, breast cancer, lung cancer, multiple myeloma, osteosarcoma, synovial sarcoma, prostate cancer, and ovarian cancer." (PMID 38255791, 2024). "In the context of breast cancer, YBX1 facilitates cell proliferation and metastasis by activating the PD-1/PD-L1 pathway." (PMID 38520004, 2024). "Knockdown of YBX1 leads to suppression of genes in breast cancer cell cycle regulation, thus inhibiting tumour growth." (PMID 38967349, 2024). "Collectively, these findings indicate that the levels of KMT2D and YBX1 are associated with the levels of c‐Myc and SENP1, suggesting a poor prognosis for individuals with breast cancer." (PMID 38967349, 2024). "In response to everolimus (mTORC1 inhibitor) or TAS0612 (multikinase inhibitor of AKT, p70S6K, and p90RSK), YBX1 phosphorylation at S102 was downregulated together with the inhibited cell growth and abrogated antiestrogen resistance in breast cancer cells." (PMID 38255791, 2024). "Numerous human cancers exhibit high expression of YBX1, such as bladder, ovarian and breast cancers, implicating YBX1 as a predictive marker for poor outcomes." (PMID 38967349, 2024). "In breast cancer, YBX1 not only initiates KLF5 (Kruppel-Like Factor 5) transcription but also recognizes 5mC-modified KLF5 mRNA to stabilize it, ultimately promoting tumor progression." (PMID 38255791, 2024). "Previous studies have demonstrated that the tumor suppressor gene BRD7 interacts with YBX1 to facilitate its degradation and consequently inhibit epithelial–mesenchymal transition and metastasis in breast cancer." (PMID 38520004, 2024). "YBX-1 exhibits high expression levels in various tumors, including breast cancer, prostate cancer, osteosarcoma, lung cancer, colorectal cancer (CRC), glioblastoma, ovarian cancer (OC), GC, and melanoma." (PMID 39062595, 2024). "2,4-dihydroxy-5-pyrimidinyl imidothiocarbomate (DPI) has been shown to hinder YBX1 nuclear translocation and its downstream target genes, which in turn inhibits breast cancer cell proliferation, migration, invasion, and metastasis." (PMID 38255791, 2024). "A previous study reported that tRF-GlyTCC is a key player in AGO2-independent RNA silencing by sequestering YBX1 and inhibiting YBX1-mediated stabilisation of pro-metastatic mRNAs in breast cancer." (PMID 36936386, 2023). "TRFs that contain a (C/G)CU(C/G/U)(C/U)C sequence motif at the 3′ end are known to interact with the RNA binding protein (RBP) YBX1 to act as a decoy to prevent YBX1 from stabilising pro-metastatic messenger RNAs (mRNAs) for translation in breast cancer." (PMID 36936386, 2023). "A peptide can target important ligands in breast cancer regulatory pathways, including chemokines, Y-box binding protein-1 (YB-1), Sin3, TNF 1-related ligand-inducing apoptosis (TRAIL), and FasL." (PMID 37513835, 2023). "A group of i-tRFs derived from tRNAGlu, tRNAAsp, tRNAGly, and tRNATyr compete with YBX1 to bind to the 3’UTRs of multiple oncogenic transcripts in breast cancer cells, thus eliminating the stabilization effect of YBX1." (PMID 36782290, 2023). "These experiments supported a model where tRF-GlyTCC suppresses CS progression by downregulating RUNX2 translation; by YBX1 displacement according to the mechanism of action revealed in breast cancer." (PMID 36936386, 2023). "In breast cancer research, two mechanisms are thought to impact the development of tRFs: evasion of hypoxia-induced tRFs and upregulation of YBX1." (PMID 36964534, 2023).
breast carcinoma (continued). "Correlation analysis in GEPIA indicated that AURKA at a high level has linkage to both YBX1 and hnRNPK with increased expression in breast cancer." (PMID 37415951, 2023). "Several tRFs also suppress breast cancer progression by displacing oncogenic transcripts from the RNA-binding protein YBX1." (PMID 35961977, 2022). "A study demonstrated that enhanced CDC20 expression in breast cancer patients was positively correlated with expression levels of YBX1." (PMID 36497125, 2022). "YBX1 acts as a reader to promote oestrogen resistance in progressive breast cancer cells, and can be inhibited by YBX1 phosphorylation inhibitor TAS0612 (a multi‐kinase inhibitor) and everolimus (a rapamycin complex 1 inhibitor)." (PMID 36169095, 2022). "An example is tRFs can suppress Breast Cancer progression by binding RNA-binding protein YBX1 to displace their 30 untranslated regions (UTRs) from YBX1, thereby inhibiting the stability of oncogene transcription." (PMID 36387119, 2022). "Specifically, in breast cancer cells, tRF-2s from tRNAGlu, tRNAAsp, tRNAGly and tRNATyr have been shown to suppress metastasis through binding to YBX1, thus inhibiting its engagement with oncogenic mRNAs." (PMID 35721477, 2022). "YBX1 is elevated in a variety of malignancies, including breast cancer; however, the prognostic role of YBX1 in TNBC is unclear." (PMID 34440660, 2021). "Overexpression and/or nuclear accumulation of YBX1 can predict poor outcomes in a variety of malignancies, including breast cancer." (PMID 34440660, 2021). "The nuclear translocation of Y-box binding protein 1 (YB-1) is responsible for CSCs features in breast cancer." (PMID 34769099, 2021). "For example, specific tRFs derived from tRNA-Glu, tRNA-Asp, tRNA-Gly, and tRNA-Tyr suppress breast cancer by binding to Y box binding protein 1 (YBX1) and destabilizing oncogenic transcripts." (PMID 33588913, 2021). "In breast cancer, tRFs compete with the RNA-binding site of the YBX1 protein to inhibit cell growth." (PMID 33406670, 2021). "YBX1 (Y-box binding protein 1) is known to bind oncogene transcripts in breast cancer and enhance their stability, which further leads to an increase of cell proliferation and promotes cancer." (PMID 34513302, 2021). "To gain insights into the significance of YBX1 in breast cancer, we analyzed YBX1 levels using the CCLE database, and results were consistent with clinical data that YBX1 was upregulated in TNBC compared to non-TNBC cell lines." (PMID 34440660, 2021). "We also found that the score of signature 3 in YBX1 high-expressing tumors was significantly higher than that in YBX1 low-expressing tumors in TCGA breast cancer datasets." (PMID 33628586, 2021). "A protein downstream of RSK2 named Y-box binding protein-1(YB-1) was reported to transform human mammary epithelial cells in the development of basal-like breast cancer." (PMID 34790230, 2021). "Our data showed that YBX1 overexpression was associated with poor survival outcomes in TNBC and luminal subtype breast cancers." (PMID 34440660, 2021). "Collectively, we identified a glycolytic signature for predicting prognoses of TNBC patients and its regulation by YBX1, providing new insights into the mechanism by which YBX1 contributes to the progression of breast cancer." (PMID 34440660, 2021). "Nuclear YBX1 has been reported to promote MET expression by directly binding to the MET promoter in basal-like breast cancers." (PMID 33312753, 2020). "In breast cancer cells, several i-tRFs were shown to compete with the 3′-untranslated regions (3′-UTRs) of oncogenes for binding to YBX1." (PMID 32890397, 2020). "tRFs also have been found to suppress the stability of multiple mRNA transcripts in breast cancer cells by displacing the 3’ untranslated regions (UTRs) of targets from the RNA-binding protein called Y box binding protein 1 (YBX1)." (PMID 32245206, 2020).
breast carcinoma (continued). "In breast cancer, inhibition of S102 phosphorylation by Akt activation was shown to reduce tumor growth, attenuate YBX1 nuclear translocation, and led to a decrease in antiestrogen drug resistance." (PMID 33375283, 2020). "In our study, we showed that EYA2 was associated with CSCs markers YBX1, KLF5, and SOX10 in breast tumor tissues, and EYA2 overexpression up-regulated YBX1 in breast cancer cell lines." (PMID 30761270, 2019). "Remarkably, YBX1 and ENO1 are two transcription factors whose targets are highly enriched for breast cancer GWAS eQTLs46, thus implicating them in breast cancer risk." (PMID 31428694, 2019). "In breast cancer cells, those tsRNAs are induced and competitively bind to YBX1, which displaces the oncogenic mRNAs from YBX1." (PMID 30781726, 2019). "In line with this, YBX1 is also more highly expressed in basal breast cancer compared to all other breast cancer subtypes." (PMID 31428694, 2019). "YBX1 has been reported to enhance EGFR transcription by directly binding to its promoter in breast cancer cells and chordoma cells." (PMID 31358880, 2019). "In breast cancer, it has been shown that there is a significant difference in the expression of YBX1 between triple-negative (TN) and ER+ subtypes." (PMID 31355251, 2019). "For module #35, while most of the genes locate on 1q34, many of the genes such as UQCRH, PSMB2, PPIH, and YBX1 are involved in RNA processing and have been identified with breast cancer in multiple studies." (PMID 30906311, 2019). "The enhanced expression of the Y-box binding protein YBX1 is consistently correlated with poor outcomes or reduced survival of breast cancer patients." (PMID 30647855, 2018). "Previous studies from many laboratories have consistently shown that the enhanced expression of YBX1 protein or mRNA in mammary tumors is significantly correlated with malignant progression or poor outcomes in patients with breast cancer." (PMID 30647855, 2018). "Determining the expression of YBX1 and its closely correlated genes will contribute to the development of precision therapeutics for breast cancer." (PMID 30647855, 2018). "In the present study, we searched a database for the top 500 genes that are positively and negatively correlated with YBX1 in breast cancer." (PMID 30647855, 2018). "YBX1 converts human mammary epithelial cells into breast cancer cells capable of anchorage-independent growth." (PMID 30647855, 2018). "Targeting YBX1 is expected to help further improve the utility of precision medicine for breast cancer." (PMID 30647855, 2018). "The nuclear expression level of YBX1 and an increased total YBX1 expression level are predictive markers for poor prognosis in patients with breast cancer, ovarian cancer, prostate cancer, and other human malignancies." (PMID 30647855, 2018). "CD49f and CD44, a stem cell marker, are transcriptionally upregulated by Y-box binding protein-1 (YB-1) in breast cancer cells, enhancing the stem-like properties of these cells, which include self-renewal, colony forming efficiency and drug resistance." (PMID 27343550, 2017). "Y-box binding protein-1 is an evolutionary conserved transcription and translation regulating protein that is overexpressed in various human malignancies, including breast cancer." (PMID 28302118, 2017). "Meanwhile, YBX1 is regarded as a poor prognostic factor in breast cancer, ovarian cancer, and gastric cancer." (PMID 29029484, 2017). "Other notable breast cancer related genes identified by super-delta include YBX1, KPNA2, SKP2, and NAT1." (PMID 29268715, 2017). "Overexpressed in breast cancer, Y-box binding protein 1 (YB-1) can be specifically bound to the A/C-rich pre-mRNA regions of CD44 to stimulate the expression of the alternative Exon V4." (PMID 28881705, 2017).
breast carcinoma (continued). "Silencing the YBX1 gene (which encodes the YB-1 protein) by small interfering RNA (siRNA) was performed in MDA-MB-231 and Hs578T breast cancer cell lines, followed by phenotypic assays including cell migration and invasion assays." (PMID 28302118, 2017). "A subgroup of genes targeted via YBX1 in CRC had been identified earlier as YBX1 target genes in breast cancer." (PMID 26779809, 2016). "When this site is disrupted, YBX1 is unable to translocate to the nucleus and activate the target genes, leading to a reduction in tumor growth in human breast cancer cells." (PMID 26318844, 2015). "The Y-Box binding protein 1 (YB-1) is a transcription factor that positively correlates with HER2 expression in breast cancer and lung cancer." (PMID 25871401, 2015). "We analyzed a large number of breast cancer cell lines with Gene Expression-Based Outcome for Breast Cancer Online (GOBO), finding that TNBC and HER2-positive breast cancer cell lines express higher levels of YBX1 and STAT3." (PMID 26512918, 2015). "To date, YBX1 has been shown to be phosphorylated only on S102 after insulin growth factor 1 (IGF-1) treatment, an event that fundamentally affects YBX1 function in human breast cancer MCF7 cells." (PMID 26318844, 2015). "Elevated expression of YBX1 is commonly observed in cancer tissues, including ~75% of human breast carcinomas." (PMID 25980435, 2015). "The Y-box binding protein-1 (YB-1), which is a member of a family of DNA-binding proteins, is an oncogenic transcription factor that is highly expressed in breast cancers, colorectal cancer and cancers of the lung, prostate, ovary and bone." (PMID 21392397, 2011). "The importance of Y-box binding protein-1 (YB-1) in the maintenance of breast cancer cell lines is well documented." (PMID 21576761, 2011). "Twenty-six of them were recently described as potential YBX1 targets in basal-like breast cancer cells as well." (PMID 21170361, 2010). "This aggressive clinical behavior is possibly mediated via different molecules such as Y-box binding protein-1, as was also shown in breast cancer." (PMID 19662216, 2007). "Our investigation reveals that YBX1 undergoes LLPS in the cytoplasm of breast cancer cells." (PMID 39976088, 2025). "HOXC-AS3 lncRNA regulates breast cancer by binding to YBX1 and activating TK1 transcription." (PMID 40799245, 2025). "Furthermore, proliferation assays and in vivo experiments similarly demonstrated that YBX1 attenuated the influence of NFIX on breast cancer cells." (PMID 40000619, 2025). "Additionally, miR-375 regulates YBX1 expression in breast cancer cells, influencing chemotherapy sensitivity and multidrug resistance." (PMID 40799245, 2025). "However, further investigation is warranted to elucidate the role of the phase‐separated environment created by YBX1 in regulating translation, post‐translational modifications, and other aspects within breast cancer cells." (PMID 39976088, 2025). "Additionally, 3D imaging using laser confocal microscopy revealed that YBX1 in the cytoplasm of breast cancer cells, as well as the in vitro purified protein, exhibited a droplet‐like distribution pattern." (PMID 39976088, 2025). "In addition, a novel family of tRFs formed from tRNA(Glu), tRNA(Asp), tRNA(Gly), and tRNA(Tyr) displace the RNA-binding protein YBX1 from several carcinogenic transcripts in breast cancer cells." (PMID 40295511, 2025). "Additionally, colocalization analyses using FISH and immunofluorescence (IF) revealed that CD2BP2‐DT and YBX1 are predominantly co‐localized in the cytoplasm of breast cancer cells." (PMID 39976088, 2025). "Indeed, as an example, i-tRFs from multiple tRNAs can interact with YBX1, leading to the destabilization of oncogenic transcripts in breast cancer (BC) cells." (PMID 39744232, 2025).
breast carcinoma (continued). "It has been found that tRFs generated from tRNAGlu, tRNAAsp, tRNAGly, and tRNATyr could bind to YBX1 and displace YBX1 from the 3’-UTRs of oncogenic mRNAs, leading to their degradation and thus suppressing breast cancer metastasis." (PMID 39039568, 2024). "Furthermore, the levels of SENP1 and c‐Myc showed a positive correlation with KMT2D and YBX1 in the breast cancer tissues analyzed as well as 17 TNBC tissues in this cohort." (PMID 38967349, 2024). "Additionally, in breast cancer, knocking down YBX1 suppresses the protein expression of glycolysis signatures Enolase 1, Glucose-6-Phosphate Isomerase, and lactate dehydrogenase A, along with a reduction in lactate secretion." (PMID 38255791, 2024). "Notably, ongoing clinical trials addressing YBX1 as a target in breast cancer and lung cancer have showcased its promise for cancer therapy." (PMID 38255791, 2024). "One notable example is the STEMVAC trial, a DNA plasmid-based vaccine encoding five antigens [Mouse Double Minute 2 Homolog (MDM2), YBX1, SRY-Box Transcription Factor 2 (SOX2), Cell Division Cycle 25B (CDC25B), Cluster of Differentiation 105 (CD105)] associated with breast cancer stem cells." (PMID 39727969, 2024). "Next, we investigated the roles of KMT2D and YBX1 using mouse models of breast cancer." (PMID 38967349, 2024). "We hypothesised that comparable to the breast cancer model, tRF-GlyTCC interacted with YBX1 to blunt a potential oncogenic protein-RNA interaction, though it was undetermined whether this interaction caused apoptosis or reduced cell viability." (PMID 36936386, 2023). "Interestingly enough, YBX1 has been reported as a prognostic marker for poor outcome and chemotherapy efficacy in colorectal cancer, breast cancer, nasopharyngeal carcinoma, and many other cancers." (PMID 35861369, 2023). "Moreover, patients suffering from breast cancer had decreased OS with YBX1 at high mRNA and protein expression." (PMID 37415951, 2023). "This motif was reported in breast cancer to be a YBX1 recognition sequence." (PMID 36936386, 2023). "In addition, endogenous tRFs can suppress human breast cancer by targeting YBX1, suggesting possible applications as pharmacological agents." (PMID 35400173, 2022). "Endogenous tRNA‐derived fragment displacement by YBX1 can suppress breast cancer progression." (PMID 36169095, 2022). "For breast cancer, YBX1 has been regarded as potential biomarker with poor outcome and silencing YBX1 could inhibit invasive potential through binding its downstream target, such as CORO1C and MMP1." (PMID 34991621, 2022). "However, the effects of YBX1 inhibitors on drug resistance in breast cancer require further investigation." (PMID 35721510, 2022). "Moreover, the inhibition of HOXC-AS3 in breast cancer cells was observed to induce cell apoptosis via the Y-box binding protein 1 (YBX1)/TK1 axis." (PMID 36613528, 2022). "However, YBX1 was expressed at lower levels in the luminal subtypes compared to HER2-positive or TNBC breast cancer." (PMID 34440660, 2021). "For example, YBX1 binds to the conserved GC-enriched sequence on the 5'-UTR of SNAIL1 mRNA, activating cap-independent translation, causing epithelial-mesenchymal transition in breast cancer cells." (PMID 33976741, 2021). "Additionally, ENO1 and LDHA were reported to promote the EMT and stemness in lung and breast cancer cells, suggesting that upregulation of glycolytic genes by YBX1 plays a crucial role in promoting tumor aggressiveness." (PMID 34440660, 2021). "Collectively, our results demonstrated that AC073352.1 promoted breast cancer metastasis and angiogenesis via binding YBX1, and it could serve as a promising, novel biomarker for prognosis and a therapeutic target in breast cancer." (PMID 34218256, 2021). "To validate the expression of YBX1 in breast cancer, we performed immunohistochemistry." (PMID 34440660, 2021).